APC (APC regulator of Wnt signaling pathway)
Diseases named in the same sentence as APC in open-access papers (continued):
Sharing a sentence is not in itself a finding about the gene and the disease.
cancer (continued). "However, it is unknown whether the NAD+ level has an impact on increasing Axin protein level by TNKS inhibition in cancer cells and whether it is sufficient to impact cancer proliferation in the APC-mutant cancer setting." (PMID 32005247, 2020). "Furthermore, inhibiting the activity of Importin-11 suppressed the growth of tumors formedby APC mutant cancer cells isolated from patients.There are many reports also showed that Importin-11 is one of main transport receptors andact as target for many cancer types." (PMID 32405167, 2020). "Furthermore, there was a strong and borderline significant trend to a worse still prognosis for BRAF mutant MSS cancers with APC mutations, compared to those without." (PMID 32384699, 2020). "Importantly, our findings unveil a class of RNF43 truncating cancer mutations that interfere with this second suppressor role to drive inappropriate Wnt pathway activation, by employing a mechanism distinct from that of RNF43 LOF or APC mutations." (PMID 32965059, 2020). "The higher proportion of cancers bearing both APC and BRAF mutation in the present study may be due to selection bias in the present series, with a higher proportion of late stage microsatellite stable cancer included." (PMID 32384699, 2020). "One possible explanation is that cancer cells may be addicted to the aberrant Wnt activation induced by oncogenic mutations, such as APC, which outcompetes the negative feedback signals to maintain the pathological Wnt activity." (PMID 30811977, 2019). "Hence, we hypothesised that the larger the APC protein and therefore more β-catenin binding activity that is retained, the more dependent cancer cells would become upon BCL9/9l for Wnt driven transformation." (PMID 30760720, 2019). "NEFH also associated with APC (another WNT pathway member, upstream of CTNNB1), through GSN, in our dataset analysis, Thus, these findings might implicate NEFH in WNT signaling in cancer, even as NEFH’s role in cancer is yet to be discovered." (PMID 31740709, 2019). "Molecular genetic testing using OncoKids Cancer Pane revealed no established variants of clinical significance, but some variants of unknown significance including APC, KMT2D, and MSH6 were found." (PMID 31702654, 2019). "While molecular genetic testing (OncoKids Cancer Panel) showed no established variants of clinical significance, it detected variants of unknown significance detected in APC, KMT2D, and MSH6." (PMID 31702654, 2019). "We also hypothesized that higher levels of DNA methylation within LINE-1 and Alu regions and within the promoter region of the hTERT gene and that lower levels of DNA methylation within the promoter regions of the APC, BRCA1, and RASSF1 genes would be associated with a reduced risk of cancer." (PMID 29953441, 2018). "This knowledge has contributed to a hypothesis that inhibiting APC/CCdc20 might be an effective anti-cancer strategy in cells treated with microtubule poisons, which has led to studies targeting APC/CCdc20 using small molecule APC/C inhibitors and by targeting Cdc20 using RNAi." (PMID 29883473, 2018). "Interestingly the BRAF-V600E positive TSA and carcinoma samples (both also containing mutation in the APC gene) clustered closely with SSP, but not FAP or other sample types." (PMID 29590112, 2018). "Hence, dysregulation of the APC-EB1, e.g. through APC mutation and/or EB1 overexpression, may promote spindle defects and aberrant chromosomal segregation which in turn initiates cancer development and progression." (PMID 28903393, 2017).
cancer (continued). "However, similar exclusion of families carrying APC, MUTYH or POLE and POLD1 mutations because known cancers other than CRC are rare or unknown in these syndrome, and exclusion based on CRC would have defeated the purpose." (PMID 28701784, 2017). "Thus, truncating cancer mutations affect the functionality but not the targeting/dynamics of APC at the centrosome." (PMID 27144584, 2016). "However, accumulating evidence suggests that targeting the APC/CFzr may also be of benefit to anti-cancer therapies." (PMID 27655696, 2016). "We review the recent advances in our understanding of how APC/C regulates G0/G1 stage and controls S-phase entry and discuss the implications of its interaction with the tumour suppressor protein retinoblastoma (pRB) for cell cycle regulation and development of anti-viral and anti-cancer drugs." (PMID 27402801, 2016). "In mitosis, cells expressing a truncated mutant form of APC tend to show a weakening of MT-chromosome attachments and exhibit irregular mitotic spindle morphologies that lead to chromosome separation errors, followed by genetic instability, a typical characteristic of cancer." (PMID 27144584, 2016). "However, together with further experimental validation, we may conclude that anticancer drugs that inhibit the expression of CTNNB1 might be useful in treating APC mutant cancers." (PMID 26937901, 2016). "Thus, we might also hypothesize that the presence of cancer may inhibit APC activation and differentiation to reduce the provision of signal 3, resulting in blunted T cell differentiation in these animals." (PMID 24796533, 2014). "Thus in future, the restoration of APC through techniques such as gene therapy or the induction of read-through stop codons may be of therapeutic benefit for APC-mutant cancers." (PMID 25301724, 2014). "However, cancer cells cannot operate the Axin/APC/GSK-3β complex by overexpression of Wnt-1." (PMID 23982808, 2013). "Therefore, inhibition of phosphorylation of APC at this site might be an effective way to normalize levels in cancer cells." (PMID 24086117, 2013). "Dysfunction of APC/CCdh1 might result in abnormal accumulation of both mitotic Cdk activity and non-Cdk kinases activity(such as Aurora A, Plk, and Nek2), leading to the development of cancer." (PMID 19216791, 2009). "Thus, dysfunction of the APC/C might lead to uncontrolled proliferation, genomic instability, and cancer." (PMID 19216791, 2009). "Therefore, it is hard to conclude that these genetic factors are the primary factors in early onset carcinogenesis, unlike germline single-gene mutations in Rb and APC that induce juvenile or early onset of cancers with high penetrance." (PMID 17919326, 2007). "Several other cancer-related alterations were detected at lower frequencies, including alterations in PTEN, PIK3CA, APC, and CTNNB1 genes." (PMID 40699829, 2025).
cancer (continued). "Together, these findings suggest a general “just-right” optimum for APC inactivation and WNT signaling, pointing to WNT hyperactivation as a potential vulnerability in cancer." (PMID 41091816, 2025). "APC codes for a TSG that induces apoptotic death and antagonises the WNT signalling pathway by inhibiting the migration of cancer cells." (PMID 40159638, 2025). "Repression of APC function is the canonical tumorigenic event in colorectal cancer, resulting in the WNT pathway dysregulation that is a pervasive feature of this cancer type." (PMID 41091816, 2025). "To further explore the respective roles of CDC20 and the APC/C in response to SAC inhibition, we analyzed genomic and transcriptomic datasets from over 1700 human cancer cell lines from the cancer Dependency Map." (PMID 39838194, 2025). "For both cohorts, we rejected the “uniform colorectal cancer risk” hypothesis that all genotypes have the same cancer progression risk (P = 3.4 × 10−4; P = 1.2 × 10−4, respectively) and the hypothesis that maximal loss of APC provides maximal colorectal cancer risk (0 not in 95% CI of mode)." (PMID 41091816, 2025). "Given that APC gene abnormalities occur in 60–70% of CRC patients, their detection serves as strong evidence of cancer origin." (PMID 39858085, 2025). "Inhibiting APC/C activity with agents like proTAME, which blocks its activation via CDC20 and CDH1, opens new avenues for disrupting cancer cell proliferation and invasion." (PMID 40136519, 2025). "APC/CCDH1 E3 ligase activity is frequently inhibited in cancer cells, likely due to hyperphosphorylation of CDH1 induced by increased CDKs activity, resulting in decreased APC/CCDH1 activity." (PMID 38622115, 2024). "Stable LS174T APC-WT or APC-m4 cell lines were used to generate 3D cellular CRC spheroids, an in vitro cancer model retaining intrinsic microenvironment properties and functional similarities to solid tumors." (PMID 38680662, 2024). "This work provides a mechanistic model implicating altered APC/C activity and spindle assembly checkpoint (SAC) signaling in the cancer cell-specific dependence on KIF18A." (PMID 38279026, 2024). "It is known that different cancer signaling pathways, such as TGF-β, mutant APC, and an enzymatically active KLK6, lead to the activation of the ERK1/2 MAP kinase during intestinal tumorigenesis." (PMID 39594797, 2024). "Similar to NUP98, NUP88 is overexpressed in a variety of human cancers, and, in this state, it sequesters the NUP98-RAE1 complex in the cytoplasm away from APC/CDH1, disturbing mitotic checkpoint control and promoting aneuploidy." (PMID 36835439, 2023).
cancer (continued). "We selected representative proteins, NEDD4, APC/CCDH1, and FBXW7, which have been extensively studied in cancer metabolism and are also involved in the DDR pathway." (PMID 37176148, 2023). "Other high-penetrant cancer genes BRCA1, APC, STK11 and moderate-penetrant genes BRIP1, CDKN2A, FANCI and MET had a similar frequency 1 (5.8%)." (PMID 37277882, 2023). "In colorectal cancer, GLS is overexpressed, and increased interaction of APC/CCDH1 and GLS by selenite treatment induces degradation of GLS that appears to contribute to inhibition of cancer progression." (PMID 37176148, 2023). "PSMG2 was involved in cancer metabolism-related pathways, including “GTP-XTP metabolism”, “ATP/ITP metabolism”, “Ubiquinone metabolism”, “Cell cycle_Role of APC in cell cycle regulation”, and “CTP/UTP metabolism”." (PMID 36619227, 2023). "In cancer, PIN1 overexpression and APC/CCDH1 inactivation reinforce each other to promote uncontrolled proliferation and tumorigenesis." (PMID 36711754, 2023). "This involvement of epigenetic changes is supported by the reported high hypermethylation levels in genes such as APC, GTSP1 and RASSF1 in morphologically normal tissue in the prostate, that have also been shown to be good predictors of cancer development." (PMID 36131292, 2022). "Mutations that facilitate the escape of β-catenin from the action of the degradation complex, such as those affecting APC or AXIN2, lead to cancer due to an increased transcription of Wnt target genes." (PMID 35158896, 2022). "Abnormal expression of Wnt ligands; loss of function due to mutations in factors that make up the destruction complex, such as APC and AXIN; and abnormalities in the activation and nuclear translocation of β-catenin can all contribute to cancer occurrence." (PMID 36224652, 2022). "A recent study demonstrated that lncRNA piR-823 overexpression in luminal BC cells activated Wnt signaling and induced cancer cell stemness by increasing DNMTs (DNMT1, DNMT3A, DNMT3B) expression and promoting adenomatous polyposis coli (APC) methylation." (PMID 35864503, 2022). "Such pathologies accumulate and lead to somatic mutations, including reading frame alterations in genes, such as APC, TGFBR2 or BAX, which results in an accelerated process of polyp-to-cancer transformation in large polyps." (PMID 36553592, 2022). "Our previous study has found that some transcriptional factors were cancer type specific methylation, including CDX2 and APC genes." (PMID 36461092, 2022). "Mutations in proto-oncogenes (e.g., KRAS, HRAS) and tumor-suppressor genes (e.g., APC, PTEN) are the primary drivers in various cancers." (PMID 36553455, 2022). "In the pan-cancer analysis of the CRISPR data, we found 104 SL pairs including KEAP1-NFE2L2, RPL22-RPL22L1, RPL22-WRN, APC-CTNNB1, and MTAP-PRMT5 from the DRIVE pan-cancer analysis." (PMID 36517508, 2022).
cancer (continued). "After mid mitosis, cell cycle proteins are separated from CDK, and in the presence of APC, M phase cyclin A and cyclin B are degraded by the proteasome through ubiquitination-dependent pathway, and CCNB1 is also known to promote cancer development." (PMID 36479313, 2022). "At the molecular level, the functional link between APC and NLGN1 in the cancer context was studied." (PMID 36056393, 2022). "Similar to other carcinoma, in EC various tumor suppressor gene promotors (MLH1, PTEN, p16, APC, MGMT, RASSF1, PR and CDH1) are hypermethylated, whereas oncogene promotors (BMP, CTCFL, PARP1, CASP8) are hypo- or demethylated." (PMID 35284957, 2022). "Although EYS has not previously been investigated in the context of prognosis, the adverse prognostic impact of APC, NOTCH1, ARID1A, and filamin A has been reported in other cancer types." (PMID 33801954, 2021). "The WNT signaling in our study is altered by the deregulation of APC, FZD1, FZD6, LRP6, and WNT10B, which are included by KEGG in the process of cancer proliferation." (PMID 34715892, 2021). "The 13 cancer-related pathways were NOTCH, APC/Wnt, Hedgehog, chromatin modification, transcriptional regulation, DNA damage control, TGF-Beta, MAPK, JAK-STAT, PI3K-AKT, driver genes, cell cycle-apoptosis, and Ras signaling pathways." (PMID 34299042, 2021). "In keeping with these findings, inactivating APC by an IR-motif-mimetic inhibitor, pro-TAME, also induced cell death in a group of cancer types." (PMID 34527589, 2021). "These implicate that S-scores and N-scores can allow one to find another type of biomarkers such as EXT1, PTCH1, KLK10, APC, TRIM13 that have strong information sensitive to early cancer." (PMID 33580150, 2021). "Protein expression by western blot indicated that APC shRNA1 cells have significantly increased CDK6, which has been frequently observed in different cancer types." (PMID 34370741, 2021). "We detected APC alterations in most small SNADETs resected via endoscopic treatment, from LGD to carcinoma samples." (PMID 34584977, 2021). "By preventing APC/C-mediated ubiquitination, AGPG protects PFKFB3 from proteasomal degradation, leading to the accumulation of PFKFB3 in cancer cells, which subsequently activates glycolytic flux and promotes cell cycle progression." (PMID 32198345, 2020). "More recently a six-gene methylation panel has been developed, termed ‘Epigenetic Cancer of the Prostate Test in Urine’ (epiCaPture), which targets GSTP1, SFRP2, IGFBP3, IGFBP7, APC and PTGS2." (PMID 33076494, 2020).